STAT3 (signal transducer and activator of transcription 3)
Diseases named in the same sentence as STAT3 in open-access papers (continued):
Sharing a sentence is not in itself a finding about the gene and the disease.
melanoma (continued). "Finally, the activated STAT3 improves the expression of VEGF in melanoma to stimulate angiogenesis of tumor and enhance the tumor vascular permeability." (PMID 29348670, 2018). "STAT3 has been shown to be constitutively phosphorylated in B16 murine melanoma cells." (PMID 30154439, 2018). "Down-regulation of STAT3 can inhibit the melanoma development and metastasis." (PMID 29348670, 2018). "However, less special drug for metastatic melanoma is approved for the first-line therapy.The Janus kinase 2 (JAK2)/signal transducer and activator of transcription 3 (STAT3) pathway is overactivated in many human cancers, including melanoma." (PMID 28570563, 2017). "Here we investigated whether an ethanolic extract of SL (SLE) exerted anti-melanoma activities by inhibiting STAT3 signaling." (PMID 28596565, 2017). "The involvement of STAT3 signaling in the anti-melanoma effects of SLE was also explored." (PMID 28596565, 2017). "Signal transducer and activator of the transcription 3 (STAT3), which is constitutively activated at 50 to 90% frequencies in diverse human cancers including melanoma, has been considered as a potential target for melanoma treatment." (PMID 28596565, 2017). "Thus, we conclude that SLE, an ethanolic extract of a herbal formula comprising SF and LJF, exerts anti-melanoma effects, and these effects are partially due to the inhibition of STAT3 signaling." (PMID 28596565, 2017). "Our findings are in agreement with previous studies that found metformin treatment suppresses the development of prostate and melanoma tumors by targeting STAT3 and NF-κB in cancer stem-like cells during the early inflammatory process (known to be associated with carcinogenesis)." (PMID 28114390, 2017). "CXCL8 (IL-8) signaling has been implicated in STAT3 activation and nuclear translocation, suggesting that inhibition of CXCR1/2 may also lead to the inhibition of STAT3 in melanoma cells." (PMID 28129639, 2017). "Taken together, these results clearly suggest that the apoptotic effect of compound 1 in melanoma cells is due to inhibition of JAK2/STAT3 signaling leading to the activation of pro-apopotic regulators and the inhibition of anti-apoptotic regulators, rather than through a general toxicity mechanism." (PMID 28570563, 2017). "Similarly, impaired DC activation as measured by IL-12 secretion has been associated with hyperactivation of both the STAT3 and MAPK signaling pathways in monocyte-derived DC exposed to conditioned media or tumor lysates from human melanomas." (PMID 29209327, 2017). "Our previous reports indicated that the aberrant ROS level could influence melanoma cell proliferation by regulating the DNA-binding activity of p-STAT3." (PMID 29312589, 2017). "Furthermore, secreted IL-6 functions in an autocrine/paracrine manner, activates the intracellular JAK/STAT3 pathway and promotes the proliferation of melanoma cells." (PMID 28222747, 2017). "Previous studies have revealed that STAT3 is constitutively activated in approximately 50–90% of melanomas, but the exact details were unknown." (PMID 28222747, 2017). "Collectively, SLE exerted potent anti-melanoma effects partially by inhibiting STAT3 signaling." (PMID 28596565, 2017). "Shp2 cooperates with c-SRC inmodulation of Stat3 phosphorylation in melanoma cells." (PMID 28085101, 2017). "Treatment of melanoma cells with Erdr1 inhibited STAT3 activity." (PMID 26784177, 2016). "Taken together, the negative correlation between Erdr1 and IL-18 suggests a potential anti-inflammatory effect that occurs through regulation of inflammatory response-related molecules such as HSP90 and STAT3, which are also candidates to be targeted for melanoma therapy." (PMID 27941650, 2016). "We found that IT significantly inhibited STAT3 activity in melanoma cells." (PMID 27323414, 2016). "It has been reported that ERK and AKT signaling inhibited STAT3 activities in human melanoma cells." (PMID 27323414, 2016).
melanoma (continued). "Therefore, targeting STAT3 assaults melanoma on multiple fronts by suppressing the oncogenic potentials due to upstream and downstream aberrations." (PMID 26911838, 2016). "Another important finding was that STAT3 activation appeared not be associated with the MEK/ERK MAPK pathway in human melanoma in vivo." (PMID 26735690, 2016). "Importantly, Stat3 activity increased melanoma invasiveness and is required for active melanogenesis by regulating tyrosinase gene expression and enzyme activity." (PMID 26830149, 2016). "The expression of activated STAT3 is higher in human melanoma BM specimens than in primary tumors." (PMID 26959886, 2016). "Specifically, STAT3 is hyperactivated in melanoma and contributes to chemoresistance." (PMID 26784177, 2016). "In addition to supporting primary tumor growth, STAT3 also drives metastatic spread of melanoma by inhibiting cell apoptosis during anoikis (anchorage-independent cell death)." (PMID 31051015, 2016). "The decreases of total STAT3 were also observed after IT treatment in the four melanoma cell lines." (PMID 27323414, 2016). "Whether PTPs are involved in apigenin-mediated STAT3 inactivation in cancer cells including melanoma cells remains unknown and deserves further investigation." (PMID 26911838, 2016). "Similarly, suppression of constitutive STAT3 in A375 melanoma cells by MEDICA was abrogated by inhibiting B-Raf(V600E) kinase by PLX4032, or by inhibiting MEK activity by PD325901." (PMID 26959890, 2016). "NS1 inhibition of STAT3 possibly linked with NOX4 inhibition may reduce cell viability and invasive properties in naïve and resistant melanoma." (PMID 27756874, 2016). "The suppression of constitutive STAT3 activation by apigenin in melanoma cells raises a possibility that apigenin may also inhibit the constitutively activated STAT3 in other cancer types, thereby providing a rationale for its use to treat other cancers." (PMID 26911838, 2016). "We next examined if apigenin affected STAT3 target genes in human melanoma cells." (PMID 26911838, 2016). "Furthermore, our in vitro analyses revealed a phosphorylation of STAT3 in the A375 melanoma cell line." (PMID 26735690, 2016). "However, following tumor challenge with the B16 melanoma cell line, splenic NK cells from STAT3-targeted mice displayed enhanced cytolytic activity compared to WT tumor-bearing mice." (PMID 27148255, 2016). "Further, subcutaneous growth of B16 melanoma cells or the MB49 bladder cancer cell line was virtually abolished in STAT3-targeted mice, suggesting that STAT3 exerts a cell-autonomous immunosuppressive effect in hematopoietic cells in the context of an antitumor response." (PMID 27148255, 2016). "IL-6, which is involved in melanoma survival, can activate STAT3 through JAK." (PMID 26784177, 2016). "In this study, we suggest that Twist1 and STAT3 activation contribute to melanoma migratory and invasive abilities because overexpression of Twist1 or STAT3 enhanced cell migratory and invasive abilities, and also reversed apigenin-mediated melanoma migration and invasion inhibition." (PMID 26911838, 2016). "Whether apigenin enhances the anti-melanoma immune responses through STAT3/VEGF inhibition needs to be further studied." (PMID 26911838, 2016). "Considering the effects of Stat3 in melanoma, we hypothesized that nifuroxazide, a potent inhibitor of Stat3, might be useful in the treatment of patients with melanoma." (PMID 26830149, 2016). "Activation of STAT3 promotes transcription of many genes that involve in melanoma metastasis." (PMID 26911838, 2016). "Immunoprecipitation assay showed that FAD104 interacted with STAT3 in melanoma cells." (PMID 25671570, 2015). "S3I-201 suppressed p-STAT3 in melanoma tissue compared to vehicle-treated tumors." (PMID 26317647, 2015).
melanoma (continued). "Inhibition of STAT3 is regarded as a potential therapeutic approach to target melanoma." (PMID 26116372, 2015). "Besides Gab1, c-Met can also activate other molecules such as STAT3 which is involved in melanoma metastasis." (PMID 25971889, 2015). "STAT3 is constitutively activated in a majority of human melanoma cell lines and tumor specimens." (PMID 26116372, 2015). "Prior studies demonstrate that BIO inhibits JAK/STAT3 signalling in human melanoma cells." (PMID 25727520, 2015). "Interestingly, a recent study indicated that STAT3 was responsible for eliciting constitutive NF-κB activity in human melanoma and prostate cancer cells." (PMID 26631279, 2015). "Studies in vitro suggested that knockdown of LIFr expression inhibited melanoma cell migration through STAT3 (signal transducer and activator of transcription 3) suppression rather than YAP (Yes-associated protein) signaling pathways." (PMID 26329521, 2015). "Mechanistically, Bay60-6583-treated melanoma tissues showed increased STAT3 activation." (PMID 26317647, 2015). "However, the specific constitution of the receptor complex and the exact cellular nature of STAT3/LIFr expression in melanoma cells needs further investigation." (PMID 26329521, 2015). "As LIF signaling is mediated through activation of the transcription factor STAT3, and as the p21-luc construct contains a STAT3 binding element, we next assessed whether TGFβ-induced p21 expression in melanoma was STAT3-dependent." (PMID 25885043, 2015). "In fact, STAT3/miR-21-signaling promotes proliferation and metastasis of B16 melanoma cells." (PMID 26116372, 2015). "In particular acquisition of resistance of melanoma cells to BRAF inhibition was found to be associated with up-regulation of PD-L1 that was dependent on the MEK and PI3K pathways and activation of c-Jun and STAT3." (PMID 25844720, 2015). "As we had hypothesized that phosphorylation at of STAT3 Y705 conferred anoikis resistance to melanoma cells, IL-6 treatment would enhance anoikis resistance in these cells." (PMID 25216522, 2014). "The extent of knockdown was comparable in all the melanoma cell lines and consequently the reduction in anoikis resistance was also similar indicating that all the metastatic melanoma cell lines were equally dependent on STAT3 for anoikis resistance." (PMID 25216522, 2014). "Therefore, STAT3 inhibitors can be used as a rational therapeutic strategy to prevent or inhibit metastasis in melanoma." (PMID 25216522, 2014). "To further test our hypothesis and to confirm the role of STAT3 in anoikis resistance, we silenced STAT3 using shRNA in four human melanoma cells lines (SK-MEL-28, SK-MEL-2, SK-MEL-5 and MeWo)." (PMID 25216522, 2014). "Here, we analyzed the role of STAT3 in anoikis resistance in melanoma cells leading to metastasis." (PMID 25216522, 2014). "Since BBMD3 was reported to inhibit the STAT3 signaling pathway in melanoma cells, we evaluated whether BBMD3 could also inhibit this pathway in human GBM stem-like cells." (PMID 24732116, 2014). "In addition, in a murine melanoma model, blockade of STAT3 enhanced the therapeutic efficacy of IFN-alpha immunotherapy." (PMID 25593920, 2014). "Although we did not detect a correlation between the STAT3 rs4796793 genotype and STAT3 mRNA levels, our in vitro results suggest that the presence of the minor allele increases the sensitivity of melanoma cells toward IFNα." (PMID 25593920, 2014). "In addition to MMP-1, expression of an active STAT3 was also found to induce transcriptional activation of the gene promoter for MMP-2 in mouse melanoma cells." (PMID 24743777, 2014). "We developed stable STAT3 knock-down (KO) melanoma cells for this purpose." (PMID 25216522, 2014). "Combination blockade of STAT3 along with vaccine therapy has shown encouraging results in melanoma." (PMID 24518612, 2014).
melanoma (continued). "Furthermore, this is the first demonstration that HSP27/p38/Akt promote doxorubicin resistance in melanoma cells, and we are the first to show that STAT3 is involved in activation of this pathway." (PMID 23383209, 2013). "We report that STAT3 knockdown with specific shRNA in melanoma cells resulted in impairment of cell survival and induction of apoptotic cell death, as evident by accumulation of the cleaved PARP and as detected by TUNEL staining, biochemical hallmarks of apoptosis." (PMID 24170218, 2013). "Importantly, the pro-tumorigenic effects of SSMC or of IL6 were completely abrogated when cells were knocked down for STAT3, thereby demonstrating the key role of STAT3 activation in the acquisition of the tumorigenic potential by melanoma cells." (PMID 24344100, 2013). "Constitutively activated STAT3 protein in melanoma could directly bind to the promoter of MMP-2 gene, thus upregulating its expression." (PMID 24199193, 2013). "It has also been shown that the treatment of human A2058 melanoma cells with a small-molecule STAT3 inhibitor, CPA-7 was effective at inhibiting the expression of HIF-1α and VEGF in vitro and tumour growth and angiogenesis of human A2058 melanoma tumours in vivo." (PMID 23301832, 2013). "Constitutively activated STAT3 is found in many cancers, including melanoma." (PMID 24170218, 2013). "We examined the effects of silencing STAT3 expression on the NFκB activity in melanoma cells." (PMID 24170218, 2013). "Moreover, number of cells with activated STAT3 in melanoma tissues was markedly elevated in those tissues with high tumor-associated B cells." (PMID 23734190, 2013). "In addition, NF-κB activation increased STAT3 activation through up-regulation of interleukin-6 (IL-6) in melanoma cells." (PMID 23402362, 2013). "The reduced survival of melanoma cells depleted of STAT3 with shRNAs could be a cumulative result of STAT3 silencing and off targets effects." (PMID 24170218, 2013). "Finally, the inhibition of STAT3 expression by siRNA abrogates the acquisition of the tumorigenic properties evoked by the in vitro exposure of melanoma cells to SSMC and completely prevents the development of xenografts." (PMID 24344100, 2013). "The STAT3 signaling pathway has been shown to be involved in the control of stemness and is activated by numerous cytokines present in the secretome of senescent melanoma, including CCL2." (PMID 24344100, 2013). "Hence, STAT3 activation is required for the acquisition of the melanoma-initiating cell properties induced by the SSMC or by IL6." (PMID 24344100, 2013). "Therefore, the SSMC induces a molecular reprogramming of melanoma cells toward a more motile and tumorigenic phenotype, mainly through STAT3 activation." (PMID 24344100, 2013). "Indeed, Mep50, cyclin D1 and STAT3 were expressed in melanoma lines, and Mep50 was predominantly cytoplasmic (data not shown)." (PMID 24098663, 2013). "STAT3 is frequently activated in various human cancers including melanoma." (PMID 23755373, 2013). "In addition, by blocking activated p-STAT3 in highly metastatic melanoma cells, the invasiveness and tumor growth were significantly suppressed." (PMID 22488042, 2012). "Because we had observed a statistically significant difference between p-STAT3 expression levels in melanoma metastasis of different tissue types, we conducted a sub-analysis of survival by tissue type using the two tissue types with the greatest number of samples." (PMID 22488042, 2012). "Activation of STAT3 signaling has an important role in melanoma oncogenesis." (PMID 23166634, 2012). "Finally, p-STAT3 levels have been found to be higher in brain metastases than in cutaneous primary melanomas, further highlighting the possible role of p-STAT3 in the development of metastases, especially to the CNS." (PMID 22488042, 2012).
melanoma (continued). "Together, these findings not only demonstrate that SOID-8 blocks the JAK2/STAT3 signaling in vitro and in vivo, but also provide a potential novel lead compound for further development of new preventive and therapeutic agents for melanoma." (PMID 23166634, 2012). "In a previous study of B16 melanoma transplant model, p-STAT3 level was likewise found to be significantly down-regulated by M-HIFU treatment, suggesting the effects of M-HIFU on STAT3 activation may be common amongst different tumors." (PMID 22911830, 2012). "To investigate whether SOID-8 can inhibit the STAT3 signaling pathway in human melanoma cells, we examined the levels of total and phosphorylated STAT3 in A2058 and A375 melanoma cells after 24 h SOID-8 treatment." (PMID 23166634, 2012). "Expression of Necdin has been previously shown to be repressed in melanoma cells so we examined whether this had a correlation with STAT3 activity." (PMID 22046235, 2011). "Furthermore, decreased expression of MMP-2 is a key reason for suppression of tumor cell invasion and metastasis following silencing of STAT-3 expression in human melanoma." (PMID 21991388, 2011). "Finally, treatment of basal pSTAT3-positive human melanoma cell lines with FLLL32 for 24 hours led to reduced STAT3 DNA binding as determined by gel shift assays and expression of the STAT3-regulated genes, cyclin D1 and survivin as measured by immunoblot." (PMID 20576164, 2010). "Fittingly, by transfecting melanoma cells with a constitutively activated mutant form of STAT3, we noted that nude mice injected with these cells had a dramatic increase in the incidence of rapidly progressing brain metastases and shortened survival when compared with wild type control." (PMID 24281074, 2010). "We hypothesized this lead compound would specifically inhibit the STAT3 signaling pathway to induce apoptosis in melanoma cells." (PMID 20576164, 2010). "The pro-apoptotic effects of FLLL32 were examined by flow cytometry following Annexin V/PI staining of a panel of metastatic human melanoma cell lines with basal STAT3 phosphorylation (A375, Hs294T, FO1, HT144, MEL-39) and the pSTAT3 negative 1106 MEL and 1259 MEL cell lines." (PMID 20576164, 2010). "Melanoma cells undergo apoptosis when either Src kinase activity or STAT3 signaling is inhibited." (PMID 20796316, 2010). "For example, in melanoma cells, IL-6/Stat3 function is modulated by the stage of tumor progression." (PMID 17925034, 2007). "In melanoma models, both monotherapy and dexamethasone combination therapy demonstrated significant tumor growth inhibition through coordinated blockade of STAT3 phosphorylation (Y705/S727) and consequent downregulation of nuclear and mitochondrial STAT3-dependent transcription." (PMID 41415576, 2025). "Thus, targeting IκBζ might constitute an attractive approach for sensitizing melanoma patients to immunotherapy, especially as IκBζ deletion would affect multiple oncogenic pathways, including NF-κB, STAT3, EZH2, and HDAC3." (PMID 40562773, 2025). "Furthermore, STAT3 is considered important in the processes regulating melanoma metastasis." (PMID 41463281, 2025). "Similarly, the KCNQ1OT1–miR-34a axis regulates STAT3 expression in melanoma." (PMID 41463281, 2025). "Furthermore, 48 h treatment with artesunate reduced p-STAT3 and p-Src expression in human A375 melanoma cells, indicating that artesunate could downregulate the Src/STAT3 signaling pathway in melanoma." (PMID 39202965, 2024). "Moreover, agents suppressing STAT3 signaling exert anti-melanoma effects." (PMID 38822350, 2024). "Therefore, in current study we hypothesized that alantolactone can inhibit STAT3 activation and increase the sensitivity of melanoma cells to MAPKi treatment." (PMID 38822350, 2024). "Furthermore, luteolin’s anti-melanoma potential was reduced by STAT3 over-activation in A375 cells." (PMID 38474604, 2024).